PBLD (phenazine biosynthesis like protein domain containing)
Description:
Functions as a positive regulator of the antiviral immune response by modulating innate immunity and viral replication by enhancing type I interferon (IFN-I) response. PBLD enhances IFN-I signaling via multiple pathways. Promotes IRF3-mediated IFN-I production and apoptosis, thereby inhibiting viral replication. Upregulates IFN-I response by activating the NF-kappaB signaling pathway, potentially through inhibition of TRIM21-mediated degradation of phosphorylated IKKbeta, thereby sustaining NF-kappaB activation to counteract viral infection. Acts as a tumor suppressor, regulating development of various cancers.
Synonyms: MAWDBP; MAWBP; FLJ14767; HEL-S-306
Tractability: PROTAC: ubiquitination databases record sites on it.
Gene: Protein-coding gene on chromosome 10 (68,282,657 to 68,334,114, reverse strand). Ensembl gene ENSG00000108187.
Subcellular location (Human Protein Atlas): Vesicles
Gene Ontology:
Molecular function: identical protein binding; protein binding; catalytic activity
Biological process: antiviral innate immune response; apoptotic process; maintenance of gastrointestinal epithelium; negative regulation of transforming growth factor beta receptor signaling pathway; positive regulation of canonical NF-kappaB signal transduction; positive regulation of type I interferon production; regulation of type I interferon production; regulation of canonical NF-kappaB signal transduction
Cellular component: cytoplasm; extracellular exosome
Genetic constraint (gnomAD): Loss-of-function variants: 19 observed, 27.93 expected, observed/expected ratio (o/e) 0.68, 90% interval 0.47 to 1. The upper end of that interval is the gene's LOEUF score, 1, which puts it in group 4 of 6, group 1 being the genes least tolerant of losing a copy. Missense variants: 292 observed, 355.08 expected, observed/expected ratio (o/e) 0.82, 90% interval 0.75 to 0.91. Synonymous variants: 112 observed, 132.37 expected, observed/expected ratio (o/e) 0.85, 90% interval 0.73 to 0.99.
Homologues: Orthologues: chimpanzee PBLD (99% identical), macaque PBLD (95% identical), dog PBLD (91% identical), rabbit PBLD (85% identical), rat Pbld1 (84% identical), mouse Pbld1 (84% identical), guinea pig PBLD (81% identical), mouse Pbld2 (81% identical), pig PBLD (76% identical), rat Pbld2 (73% identical), zebrafish pbld (56% identical), zebrafish pbld2 (55% identical), and 4 more.
Diseases named in the same sentence as PBLD in open-access papers:
PBLD is named in the same sentence as 19 diseases in open-access papers, as found by Europe PMC text mining. Sharing a sentence is not in itself a finding about the gene and the disease. The quoted sentences say what the papers report.
gastric cancer (4 papers, 2010 to 2021). A primary or metastatic malignant neoplasm involving the stomach. "Phenazine biosynthesis-like domain-containing protein (PBLD) was recently identified as a tumor suppressor in gastric cancer, hepatocellular carcinoma, and breast cancer; however, its role in UC remains unclear." (PMID 34059646, 2021).
breast carcinoma (2 papers, 2021). "Similar observations were reported in breast cancer, where circKDM4C suppresses tumor progression and enhances doxorubicin chemosensitivity by regulating miR-548p/PBLD axis." (PMID 34852843, 2021).
colitis (2 papers, 2021 to 2022). Inflammation of the colon. "In accordance with our results for the acute colitis model, epithelial PBLD deficiency also exacerbated disease severity in the chronic colitis model in mice." (PMID 34059646, 2021). "We found that the serum concentration of FITC-dextran in PBLDIEC−/− mice was significantly higher than that in WT mice, suggesting that epithelial PBLD deficiency results in increased intestinal permeability in DSS-induced colitis." (PMID 34059646, 2021). "Collectively, these results indicate that PBLD deficiency in IECs impairs intestinal barrier function in DSS-induced colitis." (PMID 34059646, 2021). "In the present study, we found that PBLD deficiency in IECs led to excessive NF-κB activation in mice with DSS-induced colitis, accompanied by increased chemokine and cytokine secretion and greater immune cell infiltration in the colon." (PMID 34059646, 2021). "Moreover, as in the acute colitis model, colon length in PBLD-deficient mice was significantly shorter and the histological score was significantly higher than in the WT mice." (PMID 34059646, 2021). "Collectively, these results suggest that PBLD deficiency in IECs may lead to greater immune cell infiltration in experimental colitis." (PMID 34059646, 2021). "We found that expression of two NF-κB signaling key molecules, p-p65 and p-IκBα, was markedly increased in IECs isolated from PBLDIEC−/− mice compared with those from WT mice in DSS-induced colitis, indicating epithelial PBLD deficiency may enhance NF-κB activity in IECs." (PMID 34059646, 2021). "Epithelial PBLD deficiency was associated with increased macrophage, monocyte, neutrophil, and CD4+ T cell infiltration in the CLP and MLN of mice with DSS-induced colitis, as demonstrated in our flow cytometry assays." (PMID 34059646, 2021). "In the present study, we demonstrated that PBLD plays a protective role in the pathogenesis of UC by using genetically engineered mice and chemical-induced mouse colitis model." (PMID 34059646, 2021). "A previous study demonstrated that the expression of PBLD was significantly decreased in mice with DSS-induced colitis; however, its repressive action on NF-κB signaling could improve intestinal barrier function and alleviate intestinal inflammation." (PMID 35893911, 2022). "Therefore, the increased levels of PBLD, FAM3D, KRT8, SULT2B1, GPA33, DEPTOR, and decreased expression of ACSL4, IFITM1 and HSD11B1 caused by mEVs has been demonstrated to attenuate colitis, implying that consumption of mEVs has the potential to improve intestinal health." (PMID 35893911, 2022). "Furthermore, PBLD overexpression in Caco2 cell monolayers resulted in the decreased epithelial permeability and improved expression of TJ proteins in inflammation, while PBLD deficiency in IECs resulted in increased intestinal permeability and decreased TJ proteins expression in DSS-induced colitis." (PMID 34059646, 2021). "Collectively, these results demonstrate that ablating PBLD expression in the intestinal epithelium of mice does not affect normal colonic functions under baseline conditions, in the absence of colitis." (PMID 34059646, 2021).
hepatocellular carcinoma (2 papers, 2016 to 2021). A malignant tumor that arises from hepatocytes. "Recent accumulating genomic and proteomic data suggested that decreased expression of phenazine biosynthesis-like domain-containing protein (PBLD) was frequently involved in hepatocellular carcinoma (HCC)." (PMID 26594798, 2016).
viral infection (2 papers, 2024 to 2026). "Moreover, macrophages with PBLD deficiency during viral infection exhibited decreased the IFN-I and ISGs expression, exacerbating viral infection." (PMID 39362857, 2024). "Taken together, PBLD plays a dual role in STING‐mediated innate immunity against viral infection and autoimmunity, highlighting its potential as a therapeutic target for both antiviral infections and autoimmune diseases." (PMID 41204829, 2026). "In general, our findings unveil the novel role of PBLD in viral infection, thus providing a potential therapeutic target and contributing to our understanding of anti-viral strategies." (PMID 39362857, 2024). "In this study, we found that PBLD plays important roles in multiple virus infections including BPIV3, SeV, VSV, and HSV-1." (PMID 39362857, 2024). "Collectively, we first discovered the new function of PBLD in viral infection, broadening our understanding of potential therapeutic targets and offering new insights for antiviral drug development." (PMID 39362857, 2024). "Despite its established role in cancer, the mechanism and function of PBLD in viral infections remain unknown." (PMID 39362857, 2024). "Furthermore, TFEB knockdown downregulated PBLD mRNA and protein expression regardless of viral infection, whereas TFEB overexpression exerted the opposite effects." (PMID 41204829, 2026).
autoimmune disease (1 paper, 2026). A disorder resulting from loss of function or tissue destruction of an organ or multiple organs, arising from humoral or cellular immune responses of the individual to their own tissue constituents. "Collectively, our findings indicate that PBLD represents a promising therapeutic target for both antiviral infections and autoimmune diseases." (PMID 41204829, 2026). "In conclusion, we identified PBLD as a positive regulator of STING‐induced type I IFN activation and elucidated the molecular regulatory network involved in PBLD‐mediated antiviral immune responses and autoimmune diseases." (PMID 41204829, 2026).
Chronic colitis (1 paper, 2021). A chronic inflammatory disease of the large intestine (colon, cecum and rectum). "During DSS-induced chronic colitis, PBLD-deficient mice lost more body weight and were more prone to early death compared with their WT counterparts, all of which survived through three cycles of DSS treatment." (PMID 34059646, 2021).
late-onset Alzheimers disease (1 paper, 2014). This is the most common form of the disease, which happens to people age 65 and older. "Other genes mapping in the deleted region, including DNAJC12 (MIM 606060), HERC4 (MIM 609248), PBLD (MIM 612189), HNRNPH3 (MIM 602324), RUFY2 (MIM 610328), STOX1 (MIM 609397), and CTNNA3 (MIM 607667), have been linked to late-onset Alzheimer’s disease (AD6; MIM 605526)." (PMID 24297458, 2014).
liver cirrhosis (1 paper, 2016). "However, the expression of PBLD was not significantly correlated with age, gender, hepatitis B surface antigen (HBsAg), hepatitis B e antigen (HBeAg), serum AFP level, liver cirrhosis, vascular invasion, intrahepatic metastasis, tumor number and tumor size." (PMID 26594798, 2016).
lupus (1 paper, 2026). "Clinically, PBLD expression is elevated in patients with systemic lupus erythematosus and positively correlates with STING‐driven type I IFN signaling." (PMID 41204829, 2026). "Clinically, PBLD expression is elevated in patients with systemic lupus erythematosus (SLE) and correlates positively with the type I IFN signature." (PMID 41204829, 2026). "Considering the prominent role of PBLD in regulating STING‐mediated type I IFN responses in the TMPD‐induced murine lupus model, we investigated its expression patterns in patients with SLE." (PMID 41204829, 2026).
tumor (10 papers, 2015 to 2026). "In conclusion, we identified PBLD as a key molecular in remolding the tumor angiogenic microenvironment, and elucidated the molecular regulatory network involved in PBLD-mediated suppression of HCC angiogenesis." (PMID 35140333, 2022). "KD of PBLD increased proliferation of BC cells, further establishing the role of PBLD as a tumor suppressor in BC." (PMID 33466455, 2021). "PBLD was previously studied in hepatocellular carcinoma and was found to be a negative regulator of various tumor progression-related signaling pathways, such as MAPK signaling, EMT, and angiogenesis." (PMID 33466455, 2021). "The prognostic role of tumor expression of PBLD was further validated in an independent cohort of 90 HCC patients." (PMID 26594798, 2016). "High PBLD expression was closely correlated with tumor differentiation (P = 0.017) and tumor stage (P = 0.038)." (PMID 26594798, 2016). "Immunofluorescence staining was then performed to evaluate the PBLD expression in selected xenograft tumor tissues." (PMID 26594798, 2016). "In addition, PBLD upregulation induced lower microvessel density (MVD) in a subcutaneously implanted tumor model in nude mice." (PMID 35140333, 2022). "PBLD is a direct target of miR-548p, which functions as a tumor suppressor in BC." (PMID 33466455, 2021). "Therefore the tumor-suppressive effects of PBLD overexpression are likely mediated through inhibition of angiogenesis, which is supported by several direct and indirect observations." (PMID 26594798, 2016). "In addition, circKDM4C experession was significantly decreased in MDA-MB-231/DOX cells and could attenuate DOX resistance by upregulating PBLD, which is a tumor suppesssor that could inhibit tumor growth." (PMID 33676555, 2021).
cancer (7 papers, 2008 to 2026). A tumor composed of atypical neoplastic, often pleomorphic cells that invade other tissues. "A gene set enrichment analysis (GSEA) of TCGA and GSE116174 datasets showed that PBLD expression is associated with cancer metastasis and survival." (PMID 35140333, 2022). "Recent studies have implicated the phenazine biosynthesis-like domain-containing protein (PBLD) in the negative regulation of the development and progression of various cancers." (PMID 39362857, 2024). "Although the role of PBLD in cancer is relatively clear, its role in UC remains unknown." (PMID 34059646, 2021). "Therefore, given the regulatory role in the inhibition of tumorigenesis-related signaling pathways, we assumed that PBLD might represent a promising therapeutic target for cancer progression mainly via ERK1/2 pathways and VEGF-A." (PMID 26594798, 2016). "Recent studies have revealed a negative correlation between PBLD expression and the progression of various cancers, including gastric, hepatocellular, and breast cancer." (PMID 39362857, 2024).
PBLD also shares sentences with these, for which no sentence is quoted: Autoimmunity (1 paper); gastric tumor (1); Hematological Disease (1); infection (1); inflammation (1); lung adenocarcinoma (1); lupus nephritis (1).